ERBB2 (erb-b2 receptor tyrosine kinase 2)
Diseases named in the same sentence as ERBB2 in open-access papers (continued):
Sharing a sentence is not in itself a finding about the gene and the disease.
breast cancer (continued). "Major Facilitator Superfamily Domain Containing 4A protein (Mfsd4a) involved in glucose transmembrane transport is on the top list of dysregulated genes, and is down-regulated 16-fold in Srsf3 KO Erbb2 breast cancer, but up-regulated 293-fold in DEN-induced Srsf3 KO liver cancer." (PMID 40568073, 2025). "In the Nurses’ Health Study II, current OC use for more than 5 years was associated with an increased risk of ER-positive/PR-positive/ERBB2-negative breast cancer, comparable to the associations we found for luminal A–like and luminal B–like tumors." (PMID 40622713, 2025). "These include the estrogen and progesterone receptor genes whose expression is strongly correlated with luminal A and luminal B phenotypes in dogs and humans and the HER-2 receptor (c-erbB-2) in those canine and human mammary cancers that are of the HER-2 positive and Luminal B phenotypes." (PMID 41012800, 2025). "Not limited to GBC, identical induction of ERBB2 i14e was also be recapitulated in breast cancer, thus indicating that the expression and function of ERBB2 i14e could be ubiquitous across varied epithelial cancer types." (PMID 39948369, 2025). "Notably, most breast cancer cell lines with ERBB2/HER2 amplification, including the ERBB2 (HER2)-enriched subtype-like SK-BR-3 (labelled with a red colored asterisk in the figure), exhibit high levels of NUPR1 mRNA expression." (PMID 39991577, 2025). "Treatment of BT-474 (ERBB2 amplified) breast cancer cells with increasing concentrations of neratinib (up to 250 nM) for 1 h led to a dose dependent decrease in the expression of downstream effectors of HER2 including phosphorylated AKT (pAKT) and ERK (pERK)." (PMID 41422272, 2025). "TILs can serve as a biomarker to identify patients with ERBB2-positive early breast cancer who may safely undergo de-escalated adjuvant therapy without compromising long-term survival outcomes." (PMID 39946142, 2025). "We hypothesized that patients from racially and ethnically minoritized groups would have persistently lower receipt of ERBB2-targeted therapies for the treatment of breast cancer." (PMID 40310643, 2025). "In this report, we demonstrated that SRSF3 at its physiological level functions as a tumor-promotor in development of Erbb2 breast cancer, but a tumor-suppressor in DEN-induced liver cancer, through regulation of RNA transcription or alternative splicing of a different set of genes." (PMID 40568073, 2025). "This follow-up analysis of the ShortHER randomized clinical trial is, to our knowledge, the first demonstration of an independent effect of TILs in terms of OS for patients with ERBB2-positive early breast cancer treated with adjuvant chemotherapy and anti-ERBB2 therapy." (PMID 39946142, 2025). "Notably, an ErbB2-overexpressing subpopulation has been identified within luminal A breast cancer cells, which were initially characterized by low ErbB2 expression." (PMID 41161384, 2025). "Given the potential of the HER2DX ERBB2 mRNA score as a predictive biomarker, particularly in the context of THP treatment, our study aims to validate the ability of the HER2DX ERBB2 mRNA score to predict survival outcomes in patients with advanced HER2+ breast cancer treated with first-line THP." (PMID 40280938, 2025). "Notably, ERBB2, a well‐known marker gene for breast cancer, was identified as a key marker for the tumor‐representing cluster 1 in the top layer." (PMID 40245302, 2025). "Additionally, investigations by Nagata and colleagues highlighted the significance of the PTEN tumor suppressor in influencing the efficacy of trastuzumab in ErbB2-amplified breast cancer." (PMID 39908697, 2025). "Breast cancer subtypes are classified as ERBB2+, luminal A, luminal B, and triple-negative." (PMID 40191734, 2025). "Similarly, Htatip2 (Tip30), a tumor suppressor in various cancers, was downregulated in Erbb2 breast cancer, but upregulated in DEN-induced liver cancer following Srsf3 knockout." (PMID 40568073, 2025).
breast cancer (continued). "Considering the high expression of SULF1 in primary breast cancer and in metastatic breast cancer with ERBB2 amplification, we further investigated mutations of SULF1 in breast cancer and their relationship with ERBB2 (HER2)." (PMID 38590118, 2025). "For example, ErbB2 (HER2) interacts with DOCK1 in breast cancer cells." (PMID 40105697, 2025). "Targeting ERBB2 contributes to the treatment of ERBB2-positive breast cancers." (PMID 39804726, 2025). "Moreover, scATAC-seq analysis revealed that DOT1L inhibition suppressed expression of ERBB2 in HER2-positive breast cancer cells." (PMID 41299712, 2025). "We aimed to assess whether macrotroponin is detectable in women with ERBB2 + breast cancer receiving sequential therapy with anthracyclines and trastuzumab." (PMID 39953627, 2025). "Moreover, we performed fluorescence in situ hybridization (FISH) imaging to visualize and quantify the P. aeruginosa in tumor tissues collected from ErbB2-overexpressed breast cancer patients who received trastuzumab treatment." (PMID 39786928, 2025). "Similarly, we also checked the activation of the ErbB2 pathway after 3oc treatment in breast cancer cells." (PMID 39786928, 2025). "In this cohort study of 274 patients with metastatic ERBB2-positive breast cancer and CNS metastasis, those with CNS-only disease had longer overall survival and a lower risk of death from any cause compared with patients with concomitant extracranial metastases." (PMID 39888615, 2025). "It is also observed in HER2+ breast cancer, because of increased signaling from ERBB2." (PMID 40940886, 2025). "A correlation was also reported between PARP1 and BRCA1/2, and at the same time, with ERBB2 and PGR in the luminal B subgroup; such results can indicate that those breast cancer patients can receive Anti-HER2 Monoclonal Antibodies and anti-PGR drugs available in the clinic at present." (PMID 40141415, 2025). "Overall, we demonstrate how ErbB2 receptor levels modulate the roles of cyclin D1 and c-Myc in the G1/S transition and suggest that variations in ErbB2 levels within breast cancer tissues confer heterogeneous sensitivity to CDK4 inhibitors, potentially complicating treatment." (PMID 41161384, 2025). "It is also reported that the ablation of CHD4 causes a downregulation of PI3K protein levels, as well as decreased phosphorylation of AKT and ERK (important pro-survival and proliferation kinases), and induces p27KIP1 upregulation, simultaneously inhibiting ERBB2+ breast cancer cell proliferation." (PMID 40004553, 2025). "This cohort study examines changes from 2010 to 2022 in use of adjuvant chemotherapy for early-stage hormone receptor–positive, ERBB2-negative breast cancer by age, genomic risk, and nodal involvement." (PMID 41632146, 2025). "The qPCR and the western blot analysis results revealed that NUPR1 positively regulates the expression of the epigenetic regulator HDAC5, the anti-apoptotic molecule BIRC5, and the mitogenic receptor ERBB2 in MCF7-TamC3 and the ERBB2-enriched subtype like SK-BR-3 breast cancer cells." (PMID 39991577, 2025). "The 17q12 copy number variation syndrome refers to copy number variations (CNV) occurring in the chromosome 17q12 region, which may affect the expression of multiple genes in this region, including ERBB2 (HER2), a known therapeutic target for breast cancer." (PMID 40170854, 2025). "However, the number of approved or potential drug targets in breast cancer patients is limited, and only 1 patient with ERBB2 amplification had a relevant target." (PMID 40730881, 2025). "When adjusted for standard of care (ESCAT I‐II) genes (i.e., PIK3CA, ESR1, and ERBB2 for breast cancer; KRAS, NRAS, and BRAF for colon cancer, etc.), 37 (3.6%), 0 (0%), 1 (0.2%), and 0 (0%) of mutant alleles would have been negative among breast, bowel, lung, and skin cancer samples, respectively." (PMID 40056420, 2025).
breast cancer (continued). "Among these, HER2 (human epidermal growth factor receptor 2, or Erb-B2 Receptor Tyrosine Kinase 2 (ERBB2)), a gene more commonly associated with breast cancer, has emerged as an important oncogenic driver in NSCLC, particularly within the adenocarcinoma subtype." (PMID 40620714, 2025). "The findings suggest that amplifications in cell cycle-related genes may confer primary resistance in HER2-low cancers, while ERBB2/CDK12 co-amplification appears to be a promising marker for favorable response in HER2-positive breast cancer." (PMID 39806366, 2025). "According to breast cancer subtype, 749 790 (73.9%) were HR-positive and ERBB2-negative, 114 249 (11.3%) were HR-negative and ERBB2-negative, 106 139 (10.5%) were HR-positive and ERBB2-positive, and 44 799 (4.4% were HR-negative and ERBB2-positive." (PMID 39853979, 2025). "We then investigated the tissue-specific KO of Srsf3 on cancer induction in two well-established mouse cancer models: activated rat c-neu (V664E) replacement of mouse Erbb2-induced breast cancer (Erbb2 breast cancer in this report), and DEN-induced liver cancer." (PMID 40568073, 2025). "What are the patterns of adjuvant chemotherapy use for early-stage hormone receptor (HR)–positive, ERBB2-negative breast cancer by genomic risk and nodal status?" (PMID 41632146, 2025). "To address these knowledge gaps, we conducted this study with the aim to assess the temporal patterns of and disparities in adjuvant chemotherapy use in early-stage HR-positive, ERBB2-negative breast cancer by age, genomic risk, and nodal involvement." (PMID 41632146, 2025). "ERBB2 gene, also known as HER2 gene, is targeted by a combination of anti-HER2 antibody drugs, pertuzumab and trastuzumab, which have demonstrated significant improvements in treatment outcomes in patients with various types of cancer, including HER2-positive breast cancer and gastric cancer." (PMID 41008893, 2025). "We excluded patients with young-onset or operable high-risk ERBB2-negative breast cancer, for whom germline GT and adjuvant PARP inhibitors are indicated." (PMID 40699578, 2025). "We also found that DOT1L inhibition downregulates ERBB2 expression in HER2-positive breast cancer cells, which may contribute to the anti-tumor effect." (PMID 41299712, 2025). "Additionally, HER-2/ERBB2-positive serous ECs are more frequently observed in patients with a previous history of breast cancer." (PMID 40452892, 2025). "MicroRNA-125b is one of the most down-regulated miRNAs in breast cancer and is able to modulate ERBB2/3 expression by acting as a double-faced gene expression regulator with tumor suppressor function in solid tumors and an oncogenic role in hematologic malignancies." (PMID 40244378, 2025). "Moreover, the USP2 inhibitor ML364 exhibited the capability to enhance ErbB2 ubiquitination and accelerate its turnover, thus inhibiting the growth of ErbB2-positive breast cancer." (PMID 40877242, 2025). "ERBB2/CDK12 co-amplification may be a potential biomarker for favorable responses in HER2-positive breast cancer." (PMID 39806366, 2025). "Also, a drug screening targeting receptor tyrosine-protein kinase erbB2 (HER2) signaling, in a biobank representing breast cancer heterogeneity with over 100 PDOs, demonstrated that sensitivity to drug treatment correlates with HER2 status." (PMID 40476002, 2025). "Additionally, ErbB2 activation can upregulate GLS1 expression in breast cancer cells through a mechanism controlled by the NF-κB pathway rather than by c-Myc, promoting glutamine utilization in cancer cells." (PMID 39973065, 2025). "We noticed that the ERBB2 (HER2)-enriched subtype-like [ER-, ERBB2 (HER2)+/high] SK-BR-3 breast cancer cells express a large amount of the nucleic NUPR1 protein endogenously, as compared to MCF7 and MCF7-TamC3 cells, and the si-NUPR1 treatment also decreased the expression of HDAC5 in SK-BR-3 cells." (PMID 39991577, 2025).
breast cancer (continued). "Thus, we examined possible relationships between the expression of NUPR1 and ERBB2 in breast cancer cells." (PMID 39991577, 2025). "Interventions that target drivers of noninitiation, particularly among racially and ethnically minoritized groups and older patients, may help ensure pharmacoequity for individuals diagnosed with ERBB2-positive breast cancer." (PMID 40310643, 2025). "These gene expression patterns exemplify how Srsf3 could act as a proto-oncogene in Erbb2 breast cancer, but a tumor suppressor in DEN-induced liver cancer." (PMID 40568073, 2025). "Srsf3 KO prevents the Erbb2 breast cancer induction but enhances DEN-induced liver carcinogenesis." (PMID 40568073, 2025). "ERBB2 is a known oncogene that is often overexpressed in breast cancer, and its high expression may indicate that the CS3 subtype has a higher proliferative potential." (PMID 40170854, 2025). "Among older women (aged ≥50 years) with ERBB2 (formerly HER2 or HER2/neu)–positive breast cancer, research has shown racial and ethnic disparities in access to ERBB2-targeted therapies, with Black women receiving treatment at lower rates than their White counterparts." (PMID 40310643, 2025). "Also targeted therapy in breast cancer was even less prevalent, with 8 patients treated with trastuzumab (1.6% of traced patients, 22.8% of 35 patients with ERBB2-positive tumors)." (PMID 39269229, 2025). "Re-biopsy of tumor tissues to assess the real-time status of ERBB2 expression in endocrine therapy-resistant ER+ breast cancer may be necessary for the decision to use Trastuzumab Deruxtecan, particularly in cases of NUPR1-overexpressing breast tumors." (PMID 39991577, 2025). "The ERBB2 gene in breast cancer is another prime example of overexpression." (PMID 40727661, 2025). "By 2020, the FDA extended neratinib’s approval to include the treatment of advanced or metastatic ErbB2-positive breast cancer patients who had received more than two prior anti-ErbB2-based regimens in the metastatic setting, when used in combination with capecitabine." (PMID 39908697, 2025). "In March 2023, the patient developed hematuria and was diagnosed with bladder metastasis based on cystoscopy and biopsy, with IHC findings indicating breast cancer origin: ER 90% (1-2+), PR <1%, HER2 (c-erbB-2) 2+, Ki-67 35%, AR 95% (3+), GATA-3+, CK (AE1/AE3)+, and P63-." (PMID 40548112, 2025). "Although ERBB2 mutations have been recognized as potential therapeutic targets, they are not standard targets in breast cancer yet." (PMID 41154672, 2025). "Antibody-drug conjugates (ADCs), such as trastuzumab emtansine and trastuzumab deruxtecan, are effective in treating erb-b2 receptor tyrosine kinase 2 (ERBB2)–positive breast cancer (BC) that has progressed on prior ERBB2-targeted therapy, warranting evaluation of their cardiotoxic profiles." (PMID 41206886, 2025). "Furthermore, besides breast carcinoma, trastuzumab therapy has also been applied to other ErbB2-positive cancers, such as gastric, gastroesophageal junction, and lung cancer." (PMID 39786928, 2025). "However, a small subset of ER+ErbB2- breast cancers are chemosensitive and achieve pathological complete responses (pCR) to chemotherapy-based neoadjuvant systemic therapy (NAT)." (PMID 39006626, 2024). "Whereas Pfkfb3 was deleted in Erbb2 mice after mammary tumors were well established and the period of observation was relatively short due to the rapid growth of the control tumors, Pfkfb3 was deleted in K-rasLA1 mice at 6 weeks of life and the mice were observed for a prolonged time period." (PMID 39001392, 2024). "Human epidermal growth factor receptor 2 (HER2)-positive breast cancer is characterized by amplification of the HER2 (ERBB2) gene and/or overexpression of the HER2 protein, which stimulates cell proliferation, survival, differentiation, angiogenesis and invasion." (PMID 38825627, 2024).
breast cancer (continued). "Importantly, approximately 50% of breast cancers lack ERBB2 gene amplification but do express HER2, are classified as “HER2 low”, and potentially also benefit from advanced therapies targeting HER210–12." (PMID 39138287, 2024). "EGFR/ErbB2 signaling pathway has been reported as important target in various kinds of cancer, including breast cancer, head and neck cancer, gastric cancer, pancreatic cancer, colon cancer, renal cell carcinoma, glioblastoma and non-small cell lung cancer, etc." (PMID 39075515, 2024). "Moreover, mouse mammary tumour models have shown that combination therapies against Fgf and ErbB2 (HER2) lead to increased anticancer effects." (PMID 39596875, 2024). "In mouse models, Jun contributes to ErbB2-induced mammary tumor cell invasion and self-renewal." (PMID 38935814, 2024). "In ErbB2+ breast cancer models, ablation of Cpt1a delays tumor onset, growth, and metastasis." (PMID 39097623, 2024). "The results of this cohort study suggest that having a higher percentage of West African genetic ancestry is associated with shorter breast cancer DFS among women with HR-positive/ERBB2-negative breast cancer." (PMID 39652347, 2024). "Biologic features may affect pathologic complete response (pCR) and event-free survival (EFS) after neoadjuvant chemotherapy plus ERBB2/HER2 blockade in ERBB2/HER2-positive early breast cancer (EBC)." (PMID 38546612, 2024). "Breast cancer is a heterogeneous disease clinically classified on the basis of the expression of estrogen and progesterone hormone receptors (ER and PR) and human epidermal growth factor receptor 2 (HER2; encoded by ERBB2), which guides treatment." (PMID 38300710, 2024). "GPX4 upregulation induced by the activation of erb-b2 receptor tyrosine kinase 2 (HER2 or ERBB2) pathway may contribute to ferroptosis resistance in luminal breast cancer cell lines." (PMID 39624080, 2024). "This case suggests that some ER+ErbB2- basal-type breast cancer patients could benefit from neoadjuvant chemoimmunotherapy, and we eagerly await further evidence from KEYNOTE-756, CheckMate 7FL, and the MammaPrint-tailored S2206 randomized phase III trials." (PMID 39006626, 2024). "ERBB2 is amplified or overexpressed in around 20% of breast cancer cases and is associated with a poor prognosis without systemic therapy." (PMID 39065193, 2024). "In this retrospective cohort study, we found that age was an independent factor associated with late DR for young patients with breast cancer diagnosed with ER-positive, ERBB2-negative subtypes." (PMID 39509133, 2024). "Indeed, asymptomatic brain metastases have been found in up to 12% of early-stage ERBB2+ breast cancer, while 25%–50% of patients with metastatic breast cancer (MBC) will develop brain metastases (BM)." (PMID 38638322, 2024). "Our study results suggest that younger age was an independent factor associated with late DR in patients with ER-positive, ERBB2-negative breast cancer." (PMID 39509133, 2024). "And the miR‐449c‐5p/JAK‐STAT/ERBB2 pathway may be a prospective therapeutic strategy for breast cancer." (PMID 38351535, 2024). "Patient 018 in cohort 4 had multiple sub-cm brain metastases from ERBB2-amplified and ERBB3-mutated breast cancer and was treated on study after receiving docetaxel, trastuzumab, and pertuzumab for primary and metastatic disease along with cerebellar radiation." (PMID 38680990, 2024). "Targeted ERBB2 mRNA levels were assessed by the Xpert® Breast Cancer STRAT4 Assay." (PMID 38321542, 2024). "Triple-negative breast cancer (TNBC), lacking the expression of receptors for estrogen and progesterone (ER and PR, respectively) and a growth factor (HER2/ErbB2), is a highly aggressive subtype of breast cancer with poor prognosis and limited options for targeted therapies." (PMID 38353696, 2024).